STAT3 (signal transducer and activator of transcription 3)
Diseases named in the same sentence as STAT3 in open-access papers (continued):
Sharing a sentence is not in itself a finding about the gene and the disease.
tumor (continued). "The data demonstrated that only USF1, YY1, STAT3 and USF2 were up-regulated in the three OS tumor samples when compared with paired normal specimens." (PMID 32269179, 2020). "Accordingly, our analysis of a subset of genes that had a significant Z score for similarity to proliferation of tumor cells predicted cell cycle progression through genes such as CDK4, HRAS, IL-4, CSF2, IFNG, IL-6 and STAT3." (PMID 33180876, 2020). "Western blot analysis of tumor tissue lysates showed that ALW reduced the phosphorylation levels of EphA2, STAT3, AKT, and ERK, consistent with the results observed in vitro and the results of stable knockdown of EphA2 observed in vivo." (PMID 32814829, 2020). "Activation of the JAK2/STAT3 pathway in CAFs provokes the release of epidermal growth factor, EGF, which promotes the EMT in tumor cells." (PMID 33363032, 2020). "Taken together, our results demonstrate that simultaneous blockade of JAK/STAT3, PI3K/AKT/mTOR, SRC and MEK/MAPK pathways results in better anti-tumor activity compared to inhibiting any one or two or three of these signaling pathways." (PMID 32927828, 2020). "F. nucleatum infection enhanced the tumor growth of CRC in a TLR4-dependent manner, and the effect involved activation of the IL-6/p-STAT3/c-MYC signaling pathway." (PMID 33488528, 2020). "Based on these findings, we assumed that STAT3, induced by regorafenib under stressful conditions in CD133-positive HCT116 and HT29 cells, plays a vital role in maintaining both tumor survival and cancer stemness." (PMID 33023006, 2020). "We showed that atorvastatin treatment decreased the levels of IL-6, p-STAT3, and TERT but increased β-gal expression and SA-β-gal activity in tumor lesions." (PMID 32257389, 2020). "MDSC recruitment to the tumor can be induced by many different factors e.g. CSF3, IL-1β, and IL-6, and subsequently lead to activation of STAT3, rendering them potent as proangiogenic and immunosuppressive cells." (PMID 31690961, 2020). "Further studies indicated that STAT3 can bind to the DMBT1 promoter region, thereby promoting tumour progression." (PMID 32760201, 2020). "Studies have shown that the mechanism of microvessel proliferation and basal membrane degradation in other diseases, such as cancers and strokes, involves the JAK2/STAT3, IL-6/JAK2/STAT3, and MMP-9 pathways, which regulate the progression of tumor metastasis." (PMID 32047820, 2020). "Taken together, our data reveal an inhibitory role for STAT3 in CD103+ cDC1 maturation and regulation of anti-tumor immunity." (PMID 31947933, 2020). "Even though this gene codes for the p85 regulatory subunit of PI3K, there is strong evidence indicating that PIK3R1 also functions as a tumor suppressor by modulating PTEN, AKT and STAT3." (PMID 32807134, 2020). "JAK/STAT signaling, especially the overactivation of STAT3 and STAT5, is known to promote tumor cell survival, proliferation, and invasion." (PMID 33202377, 2020). "Lee H demonstrated that Stat3-induced S1PR1 expression, as well as S1P/S1PR1 pathway, is important for persistent Stat3 activation in cancer cells and the tumor microenvironment and for malignant progression." (PMID 32799825, 2020). "LMP-1 activates the Janus kinase 3 (JAK3)/Signal transducer and activator of transcription 3 (STAT3) pathway, which increases the expression of vascular endothelial growth factor (VEGF) and promotes tumor metastasis and invasiveness." (PMID 32194785, 2020). "As such, phosphorylation of STAT proteins, notably STAT3, is involved in the pathogenesis of many cancers, including GBM, by promoting cell cycle progression, stimulating angiogenesis, and impairing tumour immune surveillance." (PMID 32218467, 2020). "Further research found that STING plays a vital role in regulation of MDSC differentiation and anti-tumor immunity in nasopharyngeal carcinoma by increasing the expression of SOCS1, a classic repressor of STAT3." (PMID 32972405, 2020).
tumor (continued). "PTPRK dephosphorylates and inactivates oncogenic proteins such as STAT3, EGFR and CD133, is frequently downregulated in human cancers, and is considered a tumor suppressor." (PMID 31934854, 2020). "In line with this, a novel anti-CD19 CAR-T cells with constitutive activation of STAT3 showed increased proliferation and reduced terminal differentiation of CAR-T cells, and conferred superior anti-tumor effects." (PMID 32972405, 2020). "Nobiletin inhibits CD36-dependent tumor angiogenesis, migration, invasion and sphere formation through the CD36/Stat3/Nf-Κb signaling axis." (PMID 32503228, 2020). "The immunohistochemical analysis showed that the levels of PD-L1 and p-STAT3 (Tyr705) were increased, while that of PARP1 was decreased in tumor tissue samples from mice treated with ODN1585 alone or in combination with an anti-PD-1 antibody." (PMID 32483468, 2020). "In the current study, the phosphorylation of STAT3 was suppressed when RAI14 was silenced in EC cells, and this suppression impeded tumor progression." (PMID 32957082, 2020). "For examples, PKM2 has been reported to function as a kinase of multiple proteins including histone H3, STAT3 and SREBPs to promote tumor progression; and PGK1 phosphorylates Beclin1 and pyruvate dehydrogenase kinase isozyme 1 to support tumor development." (PMID 33277463, 2020). "Nevertheless, STAT3 and STAT5 also behave as tumor suppressors in other tissues and regulate the antitumoral response of immune cells." (PMID 31963765, 2020). "The targeting of STAT3 and HSPA5 with BBI608 and HA15, respectively, significantly increased apoptosis and diminished tumorsphere formation in colorectal HCT116 and HT29 tumor cells." (PMID 33023006, 2020). "Of the seven STATs, STAT3, and STAT5 have been known to play a predominant role in tumor cell proliferation and survival." (PMID 33279931, 2020). "TB11-Fhit-transfected tumor cells showed a significant increase in the expression of IRF-1, Jak1, Ptpsh1, Stat1, Stat2, and Stat3 genes." (PMID 32545680, 2020). "Upregulation of miR-96/182/183 in BC patients due to autocrine/paracrine HGH-induced STAT3 and STAT5 activation enables tumor progression by BRMS1L." (PMID 31952344, 2020). "Although these studies provide evidence directed toward a pro-tumourigenic function of STAT3 signalling in KRAS-induced cancer, it has also been shown to act as a tumour-suppressor in LAC24." (PMID 33116132, 2020). "STAT3-high tumor cells demonstrated significantly lower half maximal inhibitory concentrations (IC50) upon treatment with STAT3 inhibitors, compared to STAT3-low cells." (PMID 31399589, 2019). "STAT3 has been shown to promote the proliferation and pathobiology of GBM tumor cores, while STAT5 affects its local invasion capabilities." (PMID 31783691, 2019). "Further in vivo studies showed that anlotinib inhibited tumor growth, induced autophagy and suppressed JAK2/STAT3/VEGFA pathway, and CQ enhanced this effect." (PMID 30755242, 2019). "Synbiotics-treatment suppressed DSS-induced expression of IL-6, STAT-3, COX-2, and TNF-α gene transcripts in normal colonic epithelium, indicating the possibility of suppressing tumor development." (PMID 31242213, 2019). "In vivo, treatment with OV alone or in combination with CDDP significantly reduced the tumor sphere-forming ability and decreased EV cargos containing mTOR, PI3K, STAT3, β-catenin, and miR-21-5p." (PMID 31878245, 2019). "Similar to STAT3, STAT5 translocates to tumor cell mitochondria, suggesting an interaction with the mitochondrial genome to promote aerobic glycolysis (the Warburg Effect), a defining characteristic of cancer cells." (PMID 31684144, 2019). "Together, these results suggest that KLF3 is involved in the tumour growth of A549 and 95D cells through regulating JAK2/STAT3 and PI3K/AKT signalling pathways in vivo." (PMID 30485570, 2019).
tumor (continued). "As already alluded above, CSCs within the OSCC tumor nests co-express OCT4, SOX2, NANOG, phosphorylated STAT3 (pSTAT3), CD133, CD44, and c-MYC." (PMID 31861233, 2019). "Both STAT3 and STAT5 activation can have a beneficial or detrimental effect on the anti-tumor response depending on the T cell type targeted." (PMID 31766350, 2019). "In vivo, EREG expression in stroma fibroblasts promoted tumor growth with high stromal α-SMA, phospho-JAK2/STAT3, and IL-6 expression and upregulated EMT in HSC3 cells." (PMID 31234944, 2019). "To understand further how DBT interfered in molecular pathways of tumor cells, we examined the expression of NF-κB, STAT3, HIF-1α, and VEGF in tumor tissues." (PMID 31781219, 2019). "In addition, PARP-1KO mice subjected to chemically-induced (AOM/dextran sodium sulfate) colorectal carcinogenesis were protected from tumor development compared to WT mice that carried significantly more tumors with a more aggressive phenotype characterized by upregulation of cyclin D1 and STAT3." (PMID 31877876, 2019). "Several studies have shown that STAT3 and STAT5 both have oncogenic activities in many cancer types, but they are activated by different mechanisms and have distinct roles in tumor development." (PMID 31534498, 2019). "Particularly STAT3 and STAT5 are activated in over 70% of all human cancer types and constitute a critical node in the signaling networks of tumor cells." (PMID 31861073, 2019). "In this study, we developed a framework to assess STAT3 activity in the TME and tumor cell compartment." (PMID 31796877, 2019). "Driven by dysregulated IL-6 family member cytokine signaling in the tumor microenvironment (TME), aberrant signal transducer and activator of transcription (STAT3) and (STAT5) activation have been identified as key contributors to tumorigenesis." (PMID 31684144, 2019). "miR-200c promoted suppressive potential of tumor MDSCs by targeting PTEN/friend of Gata 2 (FOG2), which led to STAT3 and PI3K/Akt activation." (PMID 31413755, 2019). "Studies have shown that persistent activation of STAT3 and STAT5 promote inflammation of the microenvironment, tumor proliferation, invasion and suppress anti-tumor immunity." (PMID 31684858, 2019). "Resveratrol showed anti-tumor and anti-metastatic effects by suppressing the expression of IL-10 and MCP-1 through downregulation of STAT3 signaling pathways." (PMID 30791624, 2019). "We elucidated an autocrine loop of IL-6/IGF-1R/STAT3 in EMT-mediated resistance and tumor growth in NSCLC." (PMID 31523190, 2019). "Extrinsic tumor microenvironmental factors in EOC, such as inflammatory cytokines, growth factors, hormones, and oxidative stress, can activate STAT3 and STAT5 through different mechanisms." (PMID 31861720, 2019). "The results showed significantly decreased expression of p-STAT3 and Bcl-2 in the combination therapy group (**P<0.01) E. Representative image of TUNEL assay in tumor tissue." (PMID 31777595, 2019). "It has been reported that activated STAT3 protein is expressed in over 50% of NSCLC primary tumors and cell lines while 100% of SCLC tumor tissues tested contain high level of activated STAT3 protein." (PMID 31817718, 2019). "Total STAT3, STAT3‐pY705 and STAT3‐pS727 were all increased in CD19+ Tim‐1+ cells of tumour‐bearing KO mice." (PMID 30467955, 2019). "SRC-1 also interacts with STAT1, STAT3, STAT5 and STAT6, and although STAT3 and STAT5 are considered as tumorigenic transcription factors, STAT1 is a tumor suppressor." (PMID 31178825, 2019). "Treatment with the covalent STAT3-selective inhibitor PG-S3-009 resulted in DFTD tumor cell-specific killing and reduced STAT3 phosphorylation of residue Y705." (PMID 30645971, 2019).
tumor (continued). "This study demonstrates that activation of IL-6/STAT3 regulates OCT4 expression through DNMT3b, which is an indicator of early tumor recurrence and poor prognosis of HCC." (PMID 31771617, 2019). "As discussed throughout this review, STAT3 and STAT5 have emerged as essential components involved in regulating tumor progression." (PMID 31684144, 2019). "The tyrosine phosphorylation of STAT1 and STAT3 are catalyzed by Janus kinase (JAK) and control the STAT1 and 3 downstream transcriptome, including the TGF-B1 and TNF gene network, and promote tumor progression and chemoresistance in cancer cells." (PMID 31182137, 2019). "Among the main actors in inflammatory processes, key modulators such as NF-κB, STAT-3, hypoxia-inducible factor 1 (HIF-1), IL-1, IL-6 and TNF, responsible for modulating the expression of tumor-promoting factors, stand out." (PMID 31569710, 2019). "Persistently activated STAT3 and, to some extent, STAT5 increase EOC tumor cell proliferation, survival, self-renewal, angiogenesis, metastasis, and chemoresistance while suppressing anti-tumor immunity." (PMID 31861720, 2019). "These compounds are potent, dose-dependent inhibitors of STAT3 signaling in HGG cell lines and inhibit tumor cell proliferation via apoptosis." (PMID 31361777, 2019). "(D) Western blot analysis of tumor lysates for phosphorylated EGFR (P-EGFR), phosphorylated STAT3 (P-STAT3), BAX." (PMID 30674340, 2019). "We then assessed if the differences in tumor growth and survival between the CD38-S3I-NP and S3I-NP groups correlates with a difference in STAT3 down-regulation." (PMID 30791634, 2019). "LincRNA-p21 acted as a tumor suppressor in HNSCC progression, which was attributed to direct binding to STAT3 and blocking of JAK2/STAT3 signaling." (PMID 30857539, 2019). "In the tumor tissues formed by HepG2 cells transfected with si-C1QTNF1-AS1, the expression of miR-221-3p, SOCS3, p-STAT3, c-Myc and MCL-1 was increased, decreased, increased, increased and increased, respectively." (PMID 31222560, 2019). "It is well documented that miR-21 targets tumor suppressors such as PDCD4 and phosphatase and tensin homolog (PTEN), both of which suppress expressions of PI3K, STAT3, mTOR, and β-catenin." (PMID 31878245, 2019). "Exosomes secreted under hypoxic conditions also contained more STAT3 and FAS, which can be transferred to other tumor cells to promote tumor progression and metastasis." (PMID 30925917, 2019). "Since STAT3 is active in several cell types in the TME as well as in tumor cells, being able to make a distinction between TME- and tumor-specific STAT3 activity is crucial." (PMID 31796877, 2019). "For example, pharmacological inhibition of STAT3 and STAT5 (activated by tumor-derived cytokines) decreased lipid accumulation, mitochondrial metabolism, and immunosuppressive function in MDSCs in an in vitro study." (PMID 31275326, 2019). "It has been reported that CD24 regulates NANOG expression through STAT3 phosphorylation and that pSTAT3 (Y705) bound to the NANOG promoter drives tumor onset and self-renewal in the liver." (PMID 30804456, 2019). "Tumor cell supernatant from HuCCT1 ICC cell lines induces the production of IL-10 and VEGF-A by macrophages through activation of STAT3 and polarization towards the M2 phenotype." (PMID 31480382, 2019). "More particularly, STAT3 directly induces the expression of the M2 marker CD163, both in macrophages and tumor cells." (PMID 31480382, 2019). "Collectively, our results suggest that a mesenchymal shift at recurrence originates from a STAT3/SLUG-driven precursor state transition, within the stem cell compartment of the tumor and provide new perspectives on the mechanisms driving GBM recurrence." (PMID 31652994, 2019).
tumor (continued). "Therefore, to determine whether there is any sex- or Stat3-dependent change in the expression of Stat3 activating cytokines or growth factors, we performed a qRT-PCR array for 84 cytokines and chemokines on primary tumor tissue, which was compared to transcriptomics data from SHH MB patients." (PMID 31683879, 2019). "This is through the inhibition of the NDRG2/gp130/STAT3 pathway via NDRG2 and subsequently the inhibition of tumor metastasis." (PMID 33817155, 2019). "Considering that apigenin can inhibit the activation of AKT, ERK or STAT3, the major downstream signaling pathways of EGFR, we first analyzed the antitumor effects of apigenin on EGFRm tumor cells." (PMID 31367332, 2019). "In cancer however, STAT3 and STAT5 activity becomes dysregulated, resulting in elevated STAT3/5-driven responses in tumor, stromal, and immune cells." (PMID 31684144, 2019). "To probe into the molecular mechanism that YPFS inhibited the tumor angiogenesis through affecting the activation of TSLP, we examined the expression of TSLP/TSLPR and STAT3/p-STAT3 under the treatment of the anti-TSLP antibody and YPFS in vivo and in vitro." (PMID 31885639, 2019). "The enhanced expression of miR-142-3p reduced the immunosuppressive activity of tumor BM-MDSCs, restoring CD8+ T cell proliferation through inhibiting C/EBPβ/STAT3 pathway." (PMID 31413755, 2019). "To determine what downstream signals in the tumor cells responded to IL6 secretion by TAMs, we looked at ERK, Akt, and STAT3 pathway, which all have been reported to be activated upon stimulation with IL6." (PMID 30927925, 2019). "The recent evidence from both preclinical and clinical studies have demonstrated that STAT3 plays a critical role in TNBC and STAT3 inhibitors have shown efficacy in inhibiting TNBC tumor growth and metastasis." (PMID 31088482, 2019). "Restoring IFN-β signaling to OSM-driven CSC re-engages IFN-β-mediated differentiation by repressing OSM/STAT3/SMAD3-mediated SNAIL expression, tumor initiation, and growth." (PMID 31036052, 2019). "Targeted deregulation of this feedback loop with STAT3 inhibitors not only depletes the CSC-SP within tumors, but also prompts tumor regression and profound chemosensitization." (PMID 31867574, 2019). "By doing so, the STAT3 and STAT5 activation in EOC controls properties of both tumor cells and their microenvironment, driving multiple distinct functions during EOC progression." (PMID 31861720, 2019). "In support, tumor samples harvested from the combination of pacritinib and TMZ showed the lowest level of STAT3, Sox2, PDCD4, and miR-21-5p and an increased level of GFAP." (PMID 31269723, 2019). "For example, miR-375 inhibits CRC cell proliferation mainly through targeting both JAK2/STAT3 and MAP3K8/ERK signaling pathways, miR-30a regulates cell proliferation and tumor growth of CRC by targeting CD73, miR-374b regulates CRC cell apoptosis." (PMID 31998373, 2019). "In this regard, it has been shown that CD114 anti-body therapy and/or targeting its downstream driver STAT3 depletes CSC subpopulation within NB and corresponded with reduced metastatic state, increased chemosensitization and decreased tumor growth." (PMID 31867574, 2019). "In this study, based on our in vitro and in vivo results and literature data, we introduce a novel, comprehensive network of common tumor-related proteins, such as PD-1, MET, RAF1, STAT3, BCL2, or mTOR." (PMID 31681332, 2019). "Then, phosphorylated STAT3 translocates to nucleus chaperoned by MYOF and activates downstream genes of the IL6/STAT3 pathway, thus potentiating tumor cell motility and cancer stem cell phenotype." (PMID 31828126, 2019). "Phosphorylation and acetylation profiles of STAT3 determine the differentiation and polarization of CD4+ Th17 cells that form the majority of tumor infiltrated T cells." (PMID 31861720, 2019).